ETDA (embryonic testis differentiation homolog A)
Tractability: No criterion of Open Targets' tractability assessment is met for any kind of drug.
Gene: Protein-coding gene on chromosome X (135,252,061 to 135,253,583, forward strand). Ensembl gene ENSG00000238210.
Homologues: Paralogues in human: ETDB (100% identical), ETDC (78% identical).